AR (androgen receptor)
Diseases named in the same sentence as AR in open-access papers (continued):
Sharing a sentence is not in itself a finding about the gene and the disease.
melanoma (continued). "Using this assay, we found that tumorigenic expansion and proliferative activity of multiple melanoma cell lines (WM1366, A375, and SKMEL28) was significantly reduced, in male and female mice, by AR silencing." (PMID 33112375, 2021). "Third, linc00673 is known to form a complex with androgen receptor (AR), and Brn3a activates matrix metalloproteinase 9 (MMP9), which has been shown to increase melanoma invasiveness." (PMID 34231850, 2021). "SLNCR/AR is recruited to the EGR1-bound promoter of the p21 gene and in turn represses its expression, thereby increasing proliferation of melanoma." (PMID 33050646, 2020). "Here we show that AR and EGR1 bind to the long non-coding RNA SLNCR and increase melanoma proliferation through coordinated transcriptional regulation of several growth-regulatory genes." (PMID 31116991, 2019). "Decreased cell proliferation upon inhibition of the SLNCR-AR interaction, despite increased SLNCR expression, further indicates that SLNCR and AR cooperatively regulate melanoma proliferation." (PMID 31116991, 2019). "SLNCR1, AR, and Brn3a are specifically required for transcriptional activation of matrix metalloproteinase 9 (MMP9) and increased melanoma invasion." (PMID 31921860, 2019). "We demonstrated previously that SLNCR1 binds to AR and recruits it to the MMP9 promoter and that SLNCR1 and AR are required for transcriptionally upregulating MMP9 expression and promoting melanoma invasion." (PMID 31116991, 2019). "The downregulation of the androgen receptor (AR) in dermal fibroblasts was shown to induce early CAF activation and enhance tumorigenicity of SCC and melanoma cells." (PMID 31289350, 2019). "We found that responders exhibited a significantly lower AR activity level than nonresponders in melanoma, NSCLC, and mixed tumor cohorts, respectively (P < 0.05, two-sided Wilcoxon rank-sum test)." (PMID 41486951, 2026). "Pharmacological AR inhibition (e.g., with enzalutamide) restores sensitivity to BRAF/MEKi in both sexes thus enhances treatment efficacy, and providing a compelling rationale for combination therapy approaches in melanoma." (PMID 40361336, 2025). "While traditionally overlooked in non-hormone-dependent cancers, AR is now gaining attention for its potential role in malignancies such as melanoma." (PMID 40940929, 2025). "Clinical data support this observation, suggesting that AR activity, and possibly patient sex, may impact outcomes in BRAF-mutant melanoma." (PMID 40332392, 2025). "Therefore, we analyzed the cytotoxicity, using freshly purified resting allogenic NK cells as effectors and AR-positive WM266-4, AMM16, MEL-CAL and LCM-Mel melanoma cells as targets." (PMID 39837817, 2025). "While the mechanism of AR’s observed effects is not entirely understood, recent data show that AR signaling enhances melanoma invasiveness by upregulating fucosyltransferase 4 (FUT4), leading to the dysregulation of cellular junctions." (PMID 40564107, 2025). "Findings reported in this paper show that depletion of AR positively impact the efficacy of ICIs in melanoma cells, as the anti-PD-L1 mAb, atezolizumab, increases their death, provided the absence of AR." (PMID 39837817, 2025). "In one study, primary melanoma cells (M160915) and established cell lines (A375, WM983A, UACC903) with resistance to the BRAF inhibitor dabrafenib were analyzed and it was found that the AR and its downstream pathway were upregulated." (PMID 38255778, 2024). "As the AR+ cell lines (WM793 and WM1366) used in our study were derived from vertical growth phase (VGP) melanoma lesions which have invaded into the dermis, they exhibit baseline loss of E-cadherin, and conversely, a significant number of N-cadherin-dominant AJs." (PMID 38326303, 2024). "In male melanoma, AR-positive patients exhibited worse survival rates compared to AR-negative patients, attributed to the ability of AR to enhance melanoma cell invasion through modulation of the MITF-AXL signaling pathway." (PMID 39597836, 2024).
melanoma (continued). "In this context, recent data suggest the role of androgen receptor elements in the lack of activity of ICIs in melanoma." (PMID 38396898, 2024). "In contrast, DHT stimulation failed to rescue the viability of AR- LU1205 melanoma cells under steroid hormone depletion." (PMID 38326303, 2024). "Initially, we focused on the SERPINE1 gene that is strongly upregulated in melanoma cells overexpressing AR or selected for BRAFi resistance, but not following short-term BRAFi exposure." (PMID 37838724, 2023). "AR-blockade improved sex-bias BRAF/MEK-targeted therapy response in melanoma, and enhanced CD8/T-cells activity in CRPC improving PD-1/PD-L1-inhibitors response, suggesting that AR promote targeted and immunotherapy resistance, and shows sex impact in treatment." (PMID 37941543, 2023). "AR expression also positively correlated with SERPINE1 and AXL levels in the metastatic but not primary lesions, in keeping with the complex role played by these genes in melanoma progression." (PMID 37838724, 2023). "Thus, AR gene expression is consistently induced in BRAFi-resistant melanoma cells as well as in naïve melanoma cells upon acute exposure to BRAF/MEK inhibitors, involving AR nuclear translocation and a positive feedback loop." (PMID 37838724, 2023). "For further mechanistic insights, we conducted ChIP-seq analysis using anti-AR antibodies on A375 melanoma cells with and without AR overexpression and compared the ChIP-seq profiles with those of AR in the same cells after early treatment with BRAFi (DAB)." (PMID 37838724, 2023). "Although at different levels, androgens are produced in both male and female individuals, and AR targeting provides an attractive therapy approach for improved management of melanoma irrespective of patient sex." (PMID 33112375, 2021). "Irrespective of sex, our findings point to AR signaling as a significant parameter to consider for targeted approaches to melanoma management." (PMID 33112375, 2021). "Similar IF analysis of melanoma tissue microarrays also showed variable degrees of AR expression irrespective of stages of neoplastic development or sex and age of patients." (PMID 33112375, 2021). "We performed transcriptomic analysis of three different melanoma lines, two with BRAF and one with NRAS mutations, with or without AR silencing with two different lentiviruses." (PMID 33112375, 2021). "On the other hand, SLNCR1 can also mediate gene repression: SLNCR1 recruits AR directly to EGR1-bound chromatin, where it acts as a transcription switch and represses EGR1-inducible p21 expression, therefore promoting proliferation of melanoma cells." (PMID 34638331, 2021). "Functional and mechanistic studies revealed SLNCR1 promotes melanoma invasion through upregulation of MMP9 (involved in ECM degradation) in cooperation with the brain-specific homeobox protein 3a (Brn3a) and the androgen receptor (AR)." (PMID 33203119, 2020). "A recent work conducted on a small number of patients correlated AR-positive melanoma patients with worse survival when compared to those AR negative." (PMID 32645881, 2020). "Our data implicate the regulatory triad of SLNCR, AR, and EGR1 in promoting oncogenesis and may help explain why men have a higher incidence of and more rapidly progressive melanomas compared with women." (PMID 31116991, 2019). "AR ChIP-seq identified a total of 9,974 AR binding regions (referred to as “active regions”; 5,717 for the empty vector and 8,239 for the SLNCR1-expressing vector) in hormone-deprived A375 melanoma cells." (PMID 31116991, 2019). "Both squamous cell carcinomas and melanomas showed negative staining while basal cell carcinomas showed positive staining for androgen receptor in a distant minority of cells." (PMID 28187442, 2017). "As a hypothesis-generating human anchor, in melanoma patients treated with anti-CTLA-4, AR and B7-H3 show no pre-treatment association, but a positive association emerges post-treatment." (PMID 41958557, 2026).
melanoma (continued). "Based on these insights, SARMs with antagonistic properties in melanoma tissue might be developed to block AR signaling without the systemic endocrine side effects associated with ADT or full AR antagonists such as enzalutamide." (PMID 40940929, 2025). "But later studies generally did not support this hypothesis due to a lack of apparent AR expression in most normal melanocytes or melanoma cells." (PMID 41228208, 2025). "Indeed, N-cadherin/β-catenin AJ complexes exhibit a negative correlation with activated AR only in male melanomas, supporting the notion that AR signaling promotes melanoma invasive and metastatic capacity by undermining N-cadherin-mediated AJ structures." (PMID 38326303, 2024). "Remarkably, active but not total AR positively correlates with fuco-L1CAM predominantly in stage IIB-III melanomas—pathological staging that is expected to functionally require altered cell adhesion and invasive dynamics to promote subsequent distal metastasis." (PMID 38326303, 2024). "In addition, the lncRNA SLNCR1 increases melanoma invasion by transcriptionally upregulating matrix metalloproteinase 9 (MMP9) through cooperation with brain-specific homologous box protein 3a (Brn3a) and the androgen receptor (AR)." (PMID 39060946, 2024). "Importantly, persistently elevated AR expression in melanoma cells did not block but rather subverted the transcriptional response of melanoma cells to BRAF inhibition." (PMID 37838724, 2023). "Furthermore, AR was found significantly associated with OS in RAS mutant subtypes of melanoma but not in BRAF, NF1, or triple-wild type subtypes of melanoma." (PMID 36833272, 2023). "The androgen receptor (AR) belongs to the nuclear receptor superfamily and many reports demonstrated an AR involvement in melanoma growth and invasion in vitro, whereas a clear correlation between its expression and melanoma outcome in vivo is lacking." (PMID 36614041, 2022). "The presence of the androgen receptor on the melanoma cells was inconsequential in terms of metastatic potential, as both melanoma models exhibited the same phenotype, despite differential AR expression by qPCR, although both cell lines were negative for AR by western blot." (PMID 32235862, 2020). "To test whether AR regulates melanoma proliferation in the absence of androgens, we quantified melanoma cell proliferation in hormone-depleted medium (phenol-red free medium supplemented with charcoal-stripped medium) before and after AR depletion." (PMID 31116991, 2019). "The SLNCR1/AR/Brn3a ternary complex has a high affinity for the AR and Brn3a binding sites located upstream of the MMP9 transcription start site, and the cooperative binding of AR and Brn3a to its promoter increases MMP9 expression and activity and, thus, increases the invasion of melanoma cells." (PMID 29416704, 2018). "Recently, androgen receptor (AR), but not ERs, was found to be induced by acute UVB radiation in a fish melanoma model." (PMID 35664979, 2021). "Although this suggests an androgen-dependent role of AR in melanoma proliferation, SLNCR and AR interact even in the absence of canonical ligand-induced AR activation." (PMID 31116991, 2019).
Kennedy disease (87 papers, 2006 to 2025). "In particular, androgen receptor (AR) genes, the causative genes for Kennedy disease, had a much lower number of available SNPs (114 SNPs), with an average of 28.8 informative SNPs per couple (five couples total)." (PMID 40710390, 2025). "Spinal bulbar muscular atrophy (SBMA) is caused by a polyglutamine expansion (pQe) in the N‐terminal transactivation domain of the human androgen receptor (AR‐NTD), resulting in a combination of toxic gain‐ and loss‐of‐function mechanisms." (PMID 40371721, 2025). "Kennedy’s disease, a genetic disease caused by mutations in the androgen receptor gene on the X chromosome, has symptoms very similar to ALS, including progressive myasthenia and muscle atrophy." (PMID 40149599, 2025). "Kennedy disease, an X‐linked disorder caused by an androgen receptor gene mutation, leads to progressive bulbar and limb muscle weakness." (PMID 41414721, 2025). "An increase in the number of CAG repeats (more than 38–40) in exon 1 of the AR gene leads to the development of a progressive X-linked recessive neuromuscular disease—spinal and bulbar muscular atrophy, SBMA (OMIM #313300), also known as Kennedy disease." (PMID 39596257, 2024). "To obtain further evidence regarding apparent underdiagnosis of spinal bulbar muscular atrophy, we conducted a survey of diagnostic testing results for the AR trinucleotide repeat at the Molecular Genetics Laboratory at the Alberta Children’s Hospital." (PMID 38366260, 2024). "Repeat expansions (CAG) in AR cause Kennedy’s disease, an X-linked recessive motor neuron disease, which affects hemizygous males." (PMID 38585669, 2024). "Spinal and bulbar muscular atrophy (also known as Kennedy’s disease) is due to an X-linked recessive CAG repeat expansion in the AR gene." (PMID 38132285, 2023). "Kennedy disease, reclassified as a neuromuscular disease, is an X-linked mutation of misfolded androgen receptor (AR) polyglutamine (PolyQ) accumulation in the muscles and motor neurons in the spinal tract and dorsal root ganglions." (PMID 36439561, 2022). "The expansion of a polyglutamine tract in the androgen receptor (AR) causes the spinobulbar muscular atrophy (SBMA) disease." (PMID 34575100, 2021). "In Kennedy’s disease, where the mutation in AR(CAG)n has excessively long repeats increased androgens are detrimental." (PMID 32593802, 2020). "Kennedy’s disease is caused by CAG repeat expansions in the AR gene resulting in polyglutamine (polyQ) expansion in the AR protein." (PMID 32276665, 2020). "Mutations in the AR can lead to several diseases in humans such as cancer, Kennedy’s disease (spinal and bulbar muscular atrophy) and complete androgen insensitivity syndrome (CAIS)." (PMID 32365806, 2020). "Spinobulbar muscular atrophy (SBMA) is caused by a trinucleotide repeat expansion in the androgen receptor gene on the X chromosome." (PMID 30886222, 2019). "The gene that encodes the androgen receptor has been convincingly linked to spinal and bulbar muscular atrophy (SBMA)." (PMID 29186753, 2017). "Spinal and bulbar muscular atrophy (SBMA) is a neuromuscular disorder caused by polyglutamine expansion in the androgen receptor (AR) and characterized by the loss of lower motor neurons." (PMID 28087734, 2017). "Expansion of a polyglutamine-encoding trinucleotide CAG repeat in the androgen receptor (AR) to more than 37 repeats is responsible for the X-linked neuromuscular disease spinal and bulbar muscular atrophy (SBMA)." (PMID 29124176, 2015). "There is some loss of AR function in patients with Kennedy disease, as manifested by signs of androgen insensitivity." (PMID 25928806, 2014). "Spinal and bulbar muscular atrophy is an X-linked degenerative motor neuron disease caused by an abnormal expansion in the polyglutamine encoding CAG repeat of the androgen receptor gene." (PMID 24898351, 2014).
Kennedy disease (continued). "The first discovered polyQ disorder was Spinal bulbar muscular atrophy (SBMA), also known as Kennedy’s disease which is X-linked, in 1991, a dynamic repeat mutation in the androgen receptor (AR) gene." (PMID 26331033, 2014). "Spinal and bulbar muscular atrophy is a degenerative motor neuron disease caused by CAG repeat expansion in the androgen receptor gene." (PMID 24898351, 2014). "Kennedy’s disease is caused by an expansion of a CAG repeat in the first exon of the androgen receptor gene." (PMID 25928806, 2014). "Spinal and bulbar muscular atrophy mice that carry 100 pathogenic polyglutamine repeats in the androgen receptor, and develop a late-onset neuromuscular phenotype with motor neuron degeneration, were studied." (PMID 24898351, 2014). "Spinal and bulbar muscular atrophy (SBMA, Kennedy’s disease), a late-onset neuromuscular disorder, is caused by expansion of the polymorphic polyglutamine tract in the androgen receptor (AR)." (PMID 23720649, 2013). "In males, shorter CAG repeat lengths within the AR gene are associated with a potential increase in reproductive ability, reduced risk of Kennedy's disease and perhaps greater sexual attractiveness." (PMID 22151998, 2011). "Spinal and bulbar muscular atrophy (SBMA) is a hereditary motor neuron disease caused by the expansion of a polyglutamine tract in the androgen receptor (AR)." (PMID 19399234, 2009). "However, the generation of novel transgenic mice with excessive CAG repeats in the polyglutamine tract of AR to model Kennedy’s Disease highlighted the involvement of mutated AR in androgen-dependent muscle and motoneuron pathology." (PMID 40269952, 2025). "SIRT3 reduces protein degradation in the AR100Q mouse model, used to study neurodegenerative diseases like SBMA or Kennedy's disease, where mutations in the androgen receptor (AR) gene cause toxic effects on skeletal muscle, leading to muscle weakness and neurodegeneration." (PMID 38904020, 2024). "Indeed, PQBP1 can bind to a number of causative disease proteins, such as mutated huntingtin associated with Huntington’s disease as well as the mutated androgen receptor that is associated with Kennedy’s disease." (PMID 39205314, 2024). "Spinal and bulbar muscular atrophy (SBMA), also known as Kennedy’s disease, is an X-linked recessive neuromuscular disease with slow progression, caused by mutations in the androgen receptor gene and primarily characterized by degeneration of lower motor neurons." (PMID 37628685, 2023). "Spinobulbar muscular atrophy (SBMA) is caused by CAG expansions in the androgen receptor gene." (PMID 36746939, 2023). "Patients affected by Kennedy’s disease may conceive their own biological children and, similarly to AR mutations, the expanded CAG repeats will be transmitted to the female child, who can generate a male offspring affected by Kennedy disease." (PMID 34501457, 2021). "Polyglutamine (polyQ) expansions in the androgen receptor (AR) gene cause spinal and bulbar muscular atrophy (SBMA), a neuromuscular disease characterized by lower motor neuron (MN) loss and skeletal muscle atrophy, with an unknown mechanism." (PMID 32019272, 2020). "Axonal transport is critical for proper motoneuronal functioning and is often impaired in neurodegenerative disease, including spinal bulbar muscular atrophy, an androgen-dependent neuromuscular disease linked to a polyglutamine expansion in the androgen receptor." (PMID 27517091, 2016). "Spinal and bulbar muscular atrophy (SBMA), or Kennedy disease (KD), is a rare X-linked trinucleotide repeat disorder caused by cytosine, adenine, and guanine (CAG) expansions in the androgen receptor (AR) gene." (PMID 40416113, 2025). "Only one patient (0.24%) in the amyotrophic lateral sclerosis cohort carried a hemizygous repeat expansion in AR, leading to a revised diagnosis of Kennedy’s disease." (PMID 38585669, 2024).